INS (insulin)
Diseases named in the same sentence as INS in open-access papers (continued):
Sharing a sentence is not in itself a finding about the gene and the disease.
diabetes (continued). "In summary, we examined gene expression datasets from the GEO database that are related to the diabetes and insulin response, and performed meta-analysis with the aim to identify tissue non-specific genes and pathways." (PMID 28117714, 2017). "Plasma insulin concentration is usually significantly reduced in rats with streptozotocin – induced diabetes." (PMID 28127544, 2017). "Previous studies have shown the effect of prolonged folate treatment on homocysteine levels, insulin levels and improving insulin resistance in patients with metabolic syndrome and patients with diabetes T2." (PMID 28540283, 2017). "It is important to reiterate that the approach is intended for use in average insulin-treated diabetes populations, with baseline HbA1c values within a defined average range." (PMID 27510441, 2017). "Age-related genetic factors influence the risk of T1D, but also the presence of diabetes-associated autoantibodies, the rate of progression to clinical diabetes, as well as the severity of reduced insulin secretory capacity." (PMID 28829396, 2017). "In fact, hypoglycemic events are a fairly common side effect in individuals who use insulin therapy to control diabetes." (PMID 28208654, 2017). "Monitoring of blood glucose during Ramadan is essential for patients with diabetes who hold fast during Ramadan and more particularly in patients with type-1 diabetes and also in patients with type-2 diabetes who require insulin." (PMID 28811776, 2017). "Type 2 diabetes mellitus was thought to be characterized by a severely impaired or absent GIP insulinotropic effect that most likely resulted in worsening insulin secretion." (PMID 29041949, 2017). "In conclusion, we evidenced ENT2 as a target of insulin signaling and sensitive to dysregulation in diabetes, leading to chronically increased extracellular adenosine levels and thereby setting conditions conducive to kidney injury." (PMID 28842605, 2017). "At the start of the study, the two groups had no statistical differences concerning their clinical features: average age, gender, insulin use, diabetes mellitus onset time and previous amputations." (PMID 29057063, 2017). "Repeat data from UK adults of European and South Asian ethnic origin showed changes in glucose levels, insulin sensitivity and insulin secretion several years before diabetes diagnosis in both ethnic groups." (PMID 28409212, 2017). "The meal model parameters that we estimate include the insulin volume, VI, and the glucose kinetics parameters k1 and k2, both of which are related to the severity of diabetes and also affect the glucose mean and variance." (PMID 28448498, 2017). "The aim of this study was to analyze the acute responses of bradykinin, insulin, and glycemia to exercise performed above and below lactate threshold (LT) in individuals with type 2 diabetes mellitus (T2D)." (PMID 28902927, 2017). "The earliest prospective, randomized double-blinded study to report on CV effects in T2D therapy is the University Group Diabetes Program conducted on 823 subjects assigned to the first-generation SU tolbutamide, lifestyle, insulin, or phenformin." (PMID 29270438, 2017). "Critically, we demonstrate marked abnormalities in gene expression, glucose metabolism, Ca2+ dynamics, and insulin secretion in βPax6KO mouse islets early in the development of diabetes, which are likely to play an important part in β cell secretory failure." (PMID 28377501, 2017). "We need to identify other bottlenecks in the global insulin market and to ensure that by 2022, the centenary of the first person with diabetes to be treated with insulin, all those requiring this life-saving medicine have access to affordable versions of it." (PMID 27446593, 2017). "In logistic regression analysis after adjusting for HOMA-IR, insulin, HbA1c and glucose, FGF21 remained significantly associated with diabetes." (PMID 29285020, 2017).
diabetes (continued). "Similar to insulin therapy in diabetes mellitus, GC replacement therapy should focus on avoiding serious side effects while guaranteeing an adequate substitution of the deficient hormone." (PMID 29376070, 2017). "Compared with fasting C-peptide level, postprandial C-peptide level is more capable of representing the maximal insulin secretory capacity, especially in patients with diabetes." (PMID 28881687, 2017). "His pancreatic insufficiency was treated with pancreolipase and the diabetes was well controlled with rapid-acting insulin three times daily and long-acting insulin therapy overnight." (PMID 28964265, 2017). "The present study revealed that induction of diabetes led to significant decrease in the levels of C- peptide and insulin when compared to control group." (PMID 28077129, 2017). "Before surgery, 39 patients were in treatment with metformin, 6 with insulin, and 13 with other oral diabetes medication (ODM)." (PMID 28810850, 2017). "Several mechanisms, including facilitating insulin secretion and alleviating inflammation, have been proposed to explain the effect of plasma magnesium on diabetes pathogenesis." (PMID 28986547, 2017). "Mean HbA1c value was 7.0% (53 mmol/mol), 15% received insulin therapy and average duration of diabetes was 7.2 ± 6.5 years." (PMID 28225988, 2017). "At the onset of the patient's diagnosis of diabetes, he had to use insulin injections to control blood glucose because his fasting capillary blood glucose was up to >26 mmol/L." (PMID 29069049, 2017). "The therapeutic options available for diabetes are insulin and four classes of oral anti-diabetic drugs that stimulate pancreatic insulin secretion and insulin action." (PMID 29216879, 2017). "Type 2 diabetes mellitus (T2DM) is a progressive chronic disease characterized by insulin resistance and a progressive insulin secretory defect associated with severe microvascular and macrovascular complications." (PMID 28680862, 2017). "That this occurs independently of diabetes and fasting hyperglycemia is consistent with normal insulin secretion and fasting normoglycemia in Ceacam1 mutant mice." (PMID 28396653, 2017). "They consist of a number of different highly specialized endocrine cell-types with the insulin-producing beta-cells and glucagon-producing alpha-cells being of the highest relevance to diabetes." (PMID 28473845, 2017). "Of the three types, high-molecular-weight adiponectin has the highest metabolic activity, promoting insulin sensitivity and thereby alleviating the symptoms of diabetes mellitus." (PMID 28840832, 2017). "Though modest, the ability to augment glucose stimulated insulin secretion was observed in both the GK rat and human diabetics." (PMID 28542610, 2017). "Diabetes mellitus (DM) is a metabolic disease characterized by hyperglycemia resulting from defects in insulin secretion, inefficiency of insulin action, or both." (PMID 28934129, 2017). "Glycated haemoglobin, fasting blood glucose and fasting plasma insulin, are the key markers of diabetes." (PMID 28732072, 2017). "Patients with diabetes were those who were diagnosed as such by fasting blood glucose or oral glucose tolerance test and treated with insulin or hypoglycemic drugs." (PMID 29041907, 2017). "In order to prevent the development of ketoacidosis, the insulin was taken to control the blood glucose and improve the metabolism." (PMID 28105082, 2017). "The stratified analysis comparing patients with and without symptoms with one or both positive questionnaires showed that the groups were similar in age, duration of diabetes, BMI, insulin dose and glycemic control." (PMID 29213156, 2017). "Sixteen patients (80%) were using tablets, and 4 patients (20%) were taking tablets and insulin to treat their diabetes." (PMID 28884081, 2017). "Type 2 diabetes (hereafter diabetes) is a heterogeneous disorder of glucose metabolism characterized by both reduced insulin sensitivity and pancreatic β-cell dysfunction." (PMID 28900121, 2017).
diabetes (continued). "A more recent study demonstrated that the available serum insulin in STZ induced T1D model was less than 46.8% at the point of confirmation of diabetes." (PMID 29019956, 2017). "Search terms include diabetes, insulin, trans-differentiation, stem cells, and regenerative medicine." (PMID 29096722, 2017). "Diabetes occurs when the pancreas loses its ability to produce enough insulin to compensate for the insulin resistance and as a result, blood sugar levels are no longer kept in control." (PMID 28070499, 2017). "Metformin, Glibenclamide and Insulin are all indicated for the management of Diabetes; Allopurinol for Gout; Isosorbide Dinitrate for Angina; Salbutamol for Asthma and Aspirin for the reduction of cardiovascular risk." (PMID 29214027, 2017). "In that study, no instructions were given to providers on use of the device data; this has been shown to make blood glucose monitoring less effective in non-insulin-using diabetes patients." (PMID 28698169, 2017). "These facts evidenced that diabetes altered adenosine uptake activity in response to insulin in glomeruli." (PMID 28842605, 2017). "These variations in gut microbiota were associated with diabetes risk factors such as fasting glucose, high triglycerides, low HDL and fasting insulin." (PMID 28261173, 2017). "But many large randomized trails are under progress for the prospect of possibilities of SGLT2 inhibitors of add-on therapy to insulin in type 1 diabetes mellitus (T1DM)." (PMID 28538386, 2017). "This study has shown that the mother’s involvement in the diabetes management of their children and minimal/moderate caregiver involvement in the task of insulin injection are the most important determinants for good and poor glucose control respectively." (PMID 28606170, 2017). "Diabetes is a complex and progressive disease which results from impaired insulin secretion and/or sensitivity." (PMID 29137205, 2017). "In fact, the implementation of postpartum diabetes screening was advised only to women who received insulin injections during their pregnancy." (PMID 28451031, 2017). "To dissect if diabetes medication has a direct impact on methylation, we exposed liver cells to metformin and insulin in vitro." (PMID 28947922, 2017). "Compared with the control group, glucose, triglycerides, total cholesterol, AST, ALT, BUN, fasting insulin and homeostatic model assessment insulin resistance levels in peripheral blood were significantly increased in the diabetes group." (PMID 29213335, 2017). "Type 2 diabetes mellitus (T2DM), one of the most common types of diabetes with the characteristics of insensitivity to insulin, has attracted great attention." (PMID 29479370, 2017). "We performed differential expression tests for 6889 and 7332 genes that were measured at all studies of diabetes and insulin actions, respectively, and the corresponding adjusted significance levels by Bonferroni correction were 7.26E−06 and 6.82E−6." (PMID 28117714, 2017). "This indicates that in 2001, insulin adjustment was considered part of the nurse diabetes educator role, despite insulin being rescheduled to a prescription-only medication the previous year." (PMID 28702089, 2017). "In all types of diabetes, pancreatic β cells are unable to produce insulin adequate to lower blood sugar levels, resulting in hyperglycemia." (PMID 28758131, 2017). "Specifically, several microRNAs are involved in β-cell development and function, insulin secretion, and insulin resistance in the liver, skeletal muscle, and adipose tissue, which play an important role in glucose homeostasis and the pathogenesis of diabetes." (PMID 28299324, 2017). "I am suffering from diabetes for 12 years and taking oral medicines, but later I will also need insulin and develop heart and kidney problems (F3_51 years)”." (PMID 28327202, 2017).
diabetes (continued). "Success in the use of pig insulin to control diabetes ultimately lies in its ability to mimic the activity of the human form, which is a consequence of near perfect structural isomorphism." (PMID 29086855, 2017). "Most drug treatments for AD subjects are cholinesterase inhibitors while diabetes treatments mostly involve the use of insulin secretagogues, such as sulfonylurea derivatives, or injectable insulin for blood glucose control." (PMID 28070499, 2017). "This suggests that further progress is required to ensure consistent quality of communication on discharge for patients with insulin-treated diabetes, with particular care being paid to those where a change has occurred." (PMID 28852529, 2017). "Endogenous levels of NGF have been shown to be altered in human and experimental diabetes, while p75NTR was shown to regulate glucose homeostasis and insulin sensitivity in diabetes." (PMID 28861085, 2017). "In the present study, only one of 15 patients with diabetes was insulin‐dependent, and most had adequate glycaemic control." (PMID 29951609, 2017). "Type II diabetes is the most diffused form of diabetes, characterized by disorders of insulin action, due to insulin resistance, and abnormalities in insulin secretion by β cells." (PMID 28798911, 2017). "Considering that type of diabetes and insulin are also theoretically closely related constructs, yet type of diabetes and diabetes comorbidity not necessarily, we decided to remove diabetes treatment from the analyses." (PMID 28662208, 2017). "The odds of moderate/severe anemia over no anemia increases with increasing age of the patient, female gender, comorbidities such as renal impairment, diabetes mellitus on insulin, congestive heart failure and higher ASA scores." (PMID 28777814, 2017). "Upon metformin discontinuation, the majority of patients had their diabetes medication uptitrated (in particular insulin or sulphonylurea)." (PMID 29230420, 2017). "IRI was induced at 8 weeks after streptozotocin injection and insulin was administrated from 2 weeks after the induction of diabetes until the end of the experiment." (PMID 29196746, 2017). "Post induction of diabetes in mice, the serum folate level was detected thrice during folate or insulin treatment." (PMID 28422052, 2017). "Major medications to treat diabetes involve insulin substitution or oral antidiabetic drugs, such as biguanides, sulfonylureas, meglitinide, thiazolidinedione, and dipeptidyl peptidase." (PMID 30965879, 2017). "Diabetes is a group of metabolic diseases characterized by hyperglycemia resulting from defects in insulin secretion, action, or both." (PMID 28626772, 2017). "This study provides a unique insight into the current situation regarding the quality and accuracy of insulin-related information documented for patients with diabetes who are being discharged from hospital." (PMID 28852529, 2017). "In fact while the whole of patients affected by type 1 diabetes are treated with insulin, the treatment of type 2 diabetic patients include insulin only when strategies such as weight reduction, diet and oral medications fail to control diabetes." (PMID 28724422, 2017). "Type 2 Diabetes mellitus can be treated by several types of medications such as insulin, biguanides, sulfonylureas, and TZDs." (PMID 29203903, 2017). "The analysis of hypoglycemia suggests that omarigliptin has a favorable profile compared with placebo on a background of a variety of diabetes medications, including insulin." (PMID 28893244, 2017). "Fifty percent of patients with diabetes were on insulin and 68% with OSA used continuous positive airway pressure/bilevel positive airway pressure (CPAP/BiPAP)." (PMID 28858079, 2017). "Further studies on carnosine in diabetes are warranted to investigate the mechanisms relevant for insulin sensitivity, glucose tolerance and possible implications on the inflammatory phenotype." (PMID 28281693, 2017).
diabetes (continued). "In this study, patients in the two groups had HbA1c levels above 10% and similar diabetes duration, β-cell function, and insulin resistance; however, they differed in age and body mass index (BMI)." (PMID 29180640, 2017). "There is a growing number of people suffering from diabetes which first symptoms are only visible in the pathology of insulin pathways." (PMID 29209441, 2017). "At the epicenter of diabetes is the β-cell, the most prevalent cell type within the islets of Langerhans, and the only insulin-producing cell in the body, with the actions of this hormone essential for lowering blood glucose levels to maintain euglycemia." (PMID 28424732, 2017). "This study describes an accessible means of obtaining meaningful data with respect to discharge summary information for patients who use insulin to manage their diabetes." (PMID 28852529, 2017). "The number of older patients with diabetes started on intensive insulin treatment has been increasing in recent years." (PMID 28271075, 2017). "Second, untreated patients were mainly varying in the duration and severity of their diabetes, with differing beta cell reserve, and differing insulin sensitivities." (PMID 28484269, 2017). "Among them, EN-RAGE is a novel inflammatory marker for pre-diabetes, IL17 for incident type 2 DM and IL13 for pre-diabetes, incident type 2 DM and insulin therapy start." (PMID 28258520, 2017). "The declination of insulin secretion and beta cell function was enhanced in early-onset diabetes compared with participants had diabetes onset later than 44 years." (PMID 28422176, 2017). "Diabetes mellitus (DM) is a kind of serious metabolic disease characterized by the anomaly of insulin secretion." (PMID 29073912, 2017). "We also aimed to analyze their homing properties as well as the mechanisms by which hUCWJCs promote insulin formation and improve renal damage that is typical of patients with diabetes mellitus." (PMID 29041943, 2017). "Impaired insulin secretion was reported to contribute more to the incidence of diabetes than insulin resistance." (PMID 29079813, 2017). "Hepatic overproduction of VLDL in insulin resistant state, such as diabetes and metabolic syndrome, is strongly related to VLDL1, whereas the level of VLDL2 production remains relatively normal under this condition." (PMID 29089472, 2017). "Glucose itself is a major stimulus of β-cells, insulin secretion is incremented by hyperglycemia seen in patients with diabetes." (PMID 28881687, 2017). "Pharmacological treatment of diabetes (hyperglycemia) relies on oral antihyperglycemic agents and insulin but these approaches currently used in clinical practice do not restore normal glycemic levels in most patient." (PMID 28758125, 2017). "The fundamental reasons of diabetes are a low production of insulin, the inability of the body to use it, or a combination of both (hormone which regulate carbohydrate, fat and protein metabolism)." (PMID 29222671, 2017). "Skeletal muscles account for approximately 75% of glucose uptake under insulin-stimulated conditions, thus, they are considered as an important therapeutic target for management of diabetes." (PMID 28859155, 2017). "The characteristics of the individuals with insulin-treated diabetes that were excluded from the study were similar to those that were included." (PMID 28913365, 2017). "The modeling approach is designed for ease of use and flexibility, and it is intended for predictive modeling on insulin-treated diabetes patients." (PMID 27510441, 2017). "Most of the studies analyzed T2DM as the outcome variable, with a few considering patients with insulin-requiring diabetes." (PMID 28134804, 2017). "Diabetes and obesity are reported to have a selective effect on the function of subsarcolemmal and interfibrillar mitochondria in insulin-resistant skeletal muscle." (PMID 28850625, 2017).